STAT6 (signal transducer and activator of transcription 6)
Diseases named in the same sentence as STAT6 in open-access papers (continued):
Sharing a sentence is not in itself a finding about the gene and the disease.
melanoma (15 papers, 2010 to 2025). A malignant, usually aggressive tumor composed of atypical, neoplastic melanocytes. "When p21 was knocked down, melanoma cell growth suppression was reversed, accompanied by decreased IL-4 expression and reduced STAT6 activation." (PMID 40636453, 2025). "In vitro experiments further indicated that IL-4 overexpression hampers melanoma cell proliferation through p21-mediated STAT6 pathway activation, leading to upregulated expression of apoptotic proteins." (PMID 40636453, 2025). "In this study, we focused on Smad3 and STAT6 in melanoma cells, and the phosphorylation of these two proteins was determined in western blotting assay accordingly." (PMID 39726752, 2024). "The present study demonstrates that PS inhibited B16-F0 melanoma growth and metastasis by attenuating M2 macrophage polarization via the STAT6 signaling pathway." (PMID 37175092, 2023). "Taken together, these data indicated that PS inhibited M2 polarization and attenuated B16-F0 melanoma lung metastasis in a STAT6-dependent manner." (PMID 37175092, 2023). "In a transgenic mouse model with overexpression of IL4, IL4/IL4Rα suppressed the development of melanoma through activation of the P21-mediated STAT6 pathway and inhibition of anti-apoptotic BCL2 expression." (PMID 33419470, 2021). "For example, it is reported that IL4 promoted tumor development via p21 mediated activation of STAT6 signaling pathways in IL4 downregulated melanoma models." (PMID 31540495, 2019). "We analyzed expression of IL-4, STAT6 and p21 in human melanoma tissues (Stage II–IV) and normal tissues by immunohistochemistry analysis." (PMID 26993600, 2016). "We also found higher expression of p21 as well as STAT6 in human melanoma tissues compared to normal skin tissues." (PMID 26993600, 2016). "IL-4, STAT6 and p21 are concomitantly and progressively expressed in human melanoma tissues in a cancer stage dependent manner." (PMID 26993600, 2016). "To determine the relationship between p21 expression and SK-MEL-28 and B16F10 melanoma cells growth and STAT6 activity in the inhibitory effects of IL-4, we transfected SK-MEL-28 and B16F10 melanoma cells with p21 siRNA using a transfection agent." (PMID 26993600, 2016). "Higher expression of IL-4, STAT6 and p21 in human melanoma tissue compared to normal human skin tissue was also found." (PMID 26993600, 2016). "STAT6 is also increased in colon, glioblastoma, breast, prostate tumor and melanoma compared to normal tissue." (PMID 26993600, 2016). "Thus, our data suggest that IL-4 suppresses tumor growth through p21-mediated activation of STAT6 in melanoma tumor of tissues." (PMID 26993600, 2016). "The band of STAT6 was supershifted by STAT6 specific antibody in SK-MEL-28 melanoma cells." (PMID 26993600, 2016). "Therefore, in the present study, to evaluate the role of IL-4 in skin tumor growth, we investigated whether overexpression of IL-4 inhibits melanoma cell and tumor growth through modulation of p21-mediated STAT6 pathways." (PMID 26993600, 2016). "Increased nucleus phosphorylation of STAT6 by IL-4 was also abolished by transfection with p21 siRNA in SK-MEL-28 and B16F10 melanoma cells." (PMID 26993600, 2016). "Agreed with the increment of DNA binding activity of STAT6, the phosphorylation of STAT6 in nuclei was increased by IL-4 treatment in SK-MEL-28 and B16F10 melanoma cells." (PMID 26993600, 2016). "We found that IL-4 untreated SK-MEL-28 and B16F10 melanoma cells showed lower constituted activation of STAT6 in SK-MEL-28 and B16F10 melanoma cells." (PMID 26993600, 2016). "IL-4-increased activity of STAT6 by IL-4 was also abolished by transfection with p21 siRNA in SK-MEL-28 and B16F10 melanoma cells." (PMID 26993600, 2016).
melanoma (continued). "In the present study, we found that IL-4 overexpression inhibited cell growth of cultured SK-MEL-28 human melanoma cells and B16F10 murine melanoma cells in vivo through p21-mediated activation of STAT6." (PMID 26993600, 2016). "Our data demonstrated that consistent with cancer cell growth inhibition, IL-4 induced DNA binding activity of STAT6 and nucleus phosphorylation of STAT6 were increased in a B16F10 melanoma cell and melanoma tumor model." (PMID 26993600, 2016). "In vitro study, we found that overexpression of IL-4 significantly inhibited SK-MEL-28 human melanoma cell and B16F10 murine melanoma cell growth via p21-mediated activation of STAT6 pathway as well as increased expression of apoptotic cell death proteins." (PMID 26993600, 2016).
Stroke (15 papers, 2015 to 2025). Sudden impairment of blood flow to a part of the brain due to occlusion or rupture of an artery to the brain. "In their stroke model, loss of STAT6 impaired dead neuron clearance and exacerbated functional deficits." (PMID 40822305, 2025). "Activation of the STAT6/Arg1 axis promotes efferocytosis by microglia/macrophages and contributes to inflammation resolution in mouse models of stroke." (PMID 39660125, 2024). "IL-4 is a STAT6 activator that shifts microglia/macrophages toward an anti-inflammatory phenotype following stroke and has been reported to promote neurogenesis, tissue protection, and repair." (PMID 37759938, 2023). "STAT6 activation in microglia/macrophages has been observed in the ischemic areas of a stroke mouse model and stroke patients, and STAT6 activation in microglia/macrophages is crucial for neuroprotection." (PMID 35204186, 2022). "STAT6 expression has recently been shown to be reduced within the ischemic rodent brain after induction of stroke, and treatment with flupirtine reverses this effect." (PMID 26050199, 2015). "Interestingly, in a mouse stroke model, clearance of dead cells by macrophages was regulated by PPARγ and STAT6, which also triggered the regeneration of the area around the infarction." (PMID 40867169, 2025). "Transcriptomic analyses further reveal that PPARγ and STAT6 act as potential upstream regulators that shape the pro-efferocytic and inflammation-resolving transcriptome of macrophages in the post-stroke brain, akin to their roles observed in intracerebral hemorrhage (ICH)." (PMID 39660125, 2024). "Furthermore, in stroke mice, STAT6 activation in microglia and Mφs improved efferocytosis and modulated microglia/Mφ phenotype, accelerated inflammation resolution and ameliorated stroke outcomes." (PMID 38612664, 2024). "Recent studies have shown that STAT1 antagonistic regulator STAT6 knockout prompted M/M toward a proinflammatory phenotype, along with impaired clearance of dead/dying neurons and increased cerebral inflammation and neuronal death in stroke mice." (PMID 39107960, 2024). "In stroke, the STAT6/Arg1 pathway was found to induce efferocytosis by Mφs/microglia." (PMID 35488301, 2022). "Early after stroke, STAT6 is reported to mediate effective efferocytosis and anti-inflammatory responses of microglia and STAT6/Arg1 signaling is proposed to be a viable therapeutic target to regulate microglia functions and promote long-term favorable outcomes during brain injury." (PMID 36698776, 2022). "Indeed, the STAT6/Arg1 pathway modulates microglia/macrophage phenotype while activation of STAT6 has been reported in macrophages around the ischemic lesion early after experimental stroke in mice but also in stroke patients." (PMID 36818562, 2023). "Interestingly, stroke-induced reduction of STAT6 was significantly reversed by flupirtine as well." (PMID 26050199, 2015). "Endocytosis of STAT6/ARG1 can reduce inflammation and improve the outcome of stroke by regulating the phenotypes of macrophages/microglia." (PMID 36034287, 2022). "Interleukin‐33/interleukin 1 receptor‐like 1/signal transducer and activator of transcription 6 signaling results in an anti‐inflammatory microglia reaction, which protects NG2‐glia and oligodendrocytes early after stroke and keeps white matter integrity in a long run." (PMID 36000202, 2022).
B-cell lymphoma (14 papers, 2011 to 2025). "Activating mutations in STAT6 are common in Follicular Lymphoma (FL) and transformed FL and various other B cell lymphomas." (PMID 39910284, 2025). "Activating somatic mutations in STAT6 are well documented in B cell lymphoma with amino acid D419 being a particular mutational hotspot." (PMID 36884218, 2023). "Others and we have previously reported that STAT6 is recurrently and significantly mutated in FL and other B cell lymphomas." (PMID 35851155, 2022). "In patients with primary mediastinal B-cell lymphoma, a point mutation in the STAT6 DNA-binding domain caused the sustained activation of STAT6." (PMID 34090412, 2021). "Recurrent mutations of the STAT6 DNA binding domain strongly support the involvement of STAT6 in the pathogenesis of this aggressive B-cell lymphoma." (PMID 24520283, 2014). "Gain-of-function mutations in STAT6 and STAT3 are frequently observed in B-cell lymphomas." (PMID 40243506, 2025). "Extensive analysis of the transcriptional regulation of AICDA in a murine mature B-cell lymphoma cell line had revealed that CD40L, IL-4, and TGFβ induce AICDA expression via NF-κB, Stat6 and Smad3/4 signaling, respectively." (PMID 33507341, 2021). "Interestingly, an alternative mechanism of constitutive IL-4 signaling and STAT6 activation independent of external IL-4 stimulation has been reported for another B cell lymphoma subtype, primary mediastinal B cell lymphoma (PMBL)." (PMID 35851155, 2022). "Thus, downregulation of STAT6 and c-myc may play a part in MPT0E028-induced apoptosis in B-cell lymphoma." (PMID 25669976, 2015). "However, our data show that inhibition of STAT6 and c-myc expression by MPT0E028 may not be mediated by HDACs (HDAC1, 4, and 6) inhibition in B-cell lymphoma cell lines." (PMID 25669976, 2015).
follicular lymphoma (14 papers, 2018 to 2025). Follicular lymphoma is a form of non-Hodgkin lymphoma characterized by a proliferation of B cells whose nodular structure of follicular architecture is preserved. "Recent evidence in follicular lymphoma further demonstrates that activating mutations in STAT6 sensitize tumor cells to IL-4, driving downstream mTOR pathway activation and compensating for CREBBP deficiency." (PMID 40864740, 2025). "Here, we report a kindred with STAT6 gain of function disease with severe early onset atopy and follicular lymphoma, associated with a novel germline heterozygous mutation STAT6 c.1255G > C p.D419H located in the STAT6 DNA binding domain that co-segregated with clinical disease." (PMID 37316763, 2023). "Activating mutations in STAT6, found in more than half of cases, are among the most common genetic alterations in BCL2-R-negative follicular lymphomas." (PMID 40861583, 2025). "Indeed, increased STAT6 activity without phosphorylation has previously been reported in follicular lymphoma research studying the p.D419 mutational hotspot." (PMID 36884218, 2023). "An important clinical finding in our kindred, not described in other kindreds, was the co-occurrence of follicular lymphoma (FL) with atopy in STAT6 GOF disease." (PMID 37316763, 2023). "Recurrent mutations of genes involved in epigenetic regulation (e.g. KMT2D, CREBBP, and EZH2), JAK-STAT pathway (e.g. SOCS1, STAT6), immune signaling (i.e. TNFRSF14), and BCR/NFKB signaling (e.g. CARD11, CD79B) were previously reported in follicular lymphoma cases." (PMID 35795062, 2022).
glioblastoma (14 papers, 2011 to 2026). The most malignant astrocytic tumor (WHO grade IV). "Here, we have shown that STAT6 is epigenetically silenced in some cases of malignant glioblastoma, which facilitates cancer cell survival in a hypoxic microenvironment." (PMID 31530290, 2019). "Binding of IL-13Rα1/IL-4Rα and IL-13 results in apoptosis escape in glioblastoma cells usually induced by signal transducer and STAT-6 pathways is considered another significant hypothesis in this case." (PMID 35612318, 2022). "Two reports, in glioblastoma and lung epithelial cells, showed interactions between the cytoplasmic domains of IL13RA2 and IL4R that interfere with IL4-driven STAT6 signaling." (PMID 40663259, 2025). "A pro‐GBM mechanism in which CYP2E1‐PPARγ‐STAT‐1/NF‐κB/STAT‐3/STAT‐6 axis fueled tumorigenesis by reprogramming M/Mφ and a newly developed CYP2E1 inhibitor, Q11, as a promising anti‐inflammatory agent for glioblastoma treatment is uncovered." (PMID 37283464, 2023). "The IL-4R/STAT6-dependent pathway induces the downregulation of the miR-17–92 cluster in splenocytes from C57BL/6 mice bearing B16 subcutaneous tumors and in T lymphocytes from glioblastoma multiforme (GBM) patients." (PMID 41582199, 2026).
hemangiopericytoma (14 papers, 2018 to 2025). An antiquated term that refers to benign or malignant mesenchymal neoplasms characterized by the presence of neoplastic spindle-shaped to round cells arranged around thin-walled branching vascular spaces. "Recently, positive immunostaining of STAT6 was also reported to have strong diagnostic value for hemangiopericytoma." (PMID 33204688, 2020). "The presence of focal CD34 expression and diffuse nuclear STAT6 expression supported the diagnosis of hemangiopericytoma in our clinical case." (PMID 40099070, 2025). "Dilated and branching blood vessels, STAT6 protein overexpression and NAB2-STAT6 gene fusion are common to both hemangiopericytoma and SFT accounting for difficulties in differentiation and classification of these two entities." (PMID 37533000, 2023). "The histopathology findings showed hemangiopericytoma and STAT6 and CD34 positivity after the first and second surgeries." (PMID 37554166, 2023). "Both the SFT and hemangiopericytoma (HPC) showed 12q13 inversion and NAB-2 and STAT-6 gene fusion." (PMID 35641960, 2022). "SFT and hemangiopericytoma were previously considered distinct; however, as most tumors exhibit the characteristic NGFI‐A‐binding protein 2 (NAB2)‐signal transducer and activator of transcription 6 (STAT6) gene fusion, they have been recognized as a single disease." (PMID 40879518, 2025).
sarcoma (14 papers, 2016 to 2025). A usually aggressive malignant neoplasm of the soft tissue or bone. "Immunohistochemical straining for STAT6 and fusion analysis using the ArcherDX FusionPlex sarcoma kit, showing a NAB2 (exon 4)-STAT6 (exon 2) fusion, corroborated the biopsy diagnosis of SFT." (PMID 39583332, 2024).
soft tissue tumors (14 papers, 2015 to 2025). "In SFT, TFE3 immunohistochemical staining is a useful diagnostic marker and can be combined with STAT6 for better diagnosis, as very few soft tissue tumours are TFE3 positive." (PMID 32566457, 2020). "Strong nuclear staining for STAT6 has been used to reliably differentiate SFTs from other soft tissue tumors." (PMID 40099070, 2025). "Since relatively few soft tissue tumors are TFE3 positive, TFE3 is fruitful as a diagnostic marker for SFT and can be paired with STAT6 for a more accurate diagnosis." (PMID 38659562, 2024). "Lastly, SRF::STAT6 fusion was reported in a case of deep soft-tissue tumor of the arm in a 15-year-old boy, expressing a full smooth-muscle phenotype and overlapping features with the SRF::RELA myofibromas." (PMID 36421692, 2022). "Several large-scale studies on soft tissue tumors showed that nuclear positivity for the STAT6 antibody and STAT6 fusion gene were mostly characterized by SFT." (PMID 34350112, 2021). "IHC of the diagnostic markers STAT6 and GRIA2 would be important in differentiating SFT from other soft tissue tumors." (PMID 26337721, 2015). "For example, in the case of STAT6, which was immunopositive in the recurrent tumor, nuclear expression can be found in almost all cases related to SFTs, but is limited in other examples of soft tissue neoplasms." (PMID 40861561, 2025). "However, few recent studies have reported STAT6 expression in other soft tissue neoplasms." (PMID 33879215, 2021). "Surprisingly, only 2.3–2.5 % of non-SFT soft tissue tumors exhibited positive and weak reactions in IHC with anti-STAT6 antibodies." (PMID 26337721, 2015). "Additionally, strong nuclear STAT6 IHC staining, which can be used instead of costly molecular tests for detecting NAB2-STAT6 fusion genes, has been used to reliably differentiate SFT from other soft tissue tumors, tumors of the head and neck, gynecologic tract, and prostate." (PMID 37742027, 2023).
inflammatory bowel disease (13 papers, 2016 to 2026). A spectrum of small and large bowel inflammatory diseases of unknown etiology. "STAT6 activation has been detected in the inflamed colonic epithelium of patients with active inflammatory bowel disease (IBD)." (PMID 38831059, 2024). "STAT6 activation was detected in the inflamed colonic epithelium of patients with active inflammatory bowel diseases, and the activated STAT6 destroyed the tight junction integrity in the colonic epithelium." (PMID 35204186, 2022). "p-STAT6 was observed in intestinal epithelial cells of patients with inflammatory bowel disease." (PMID 32301489, 2020). "Collectively, our study indicated that commensal microbe-derived butyrate is a novel activator of STAT6-mediated transcription through H3K9 acetylation driving M2 macrophage polarization, and delineated new insights into the immune interplay underlying inflammatory bowel disease." (PMID 27094081, 2016). "In sum, our studies indicated that commensal microbe-derived butyrate enhanced the IL-4-mediated STAT6 transcription, achieved through H3K9 acetylation to enhance M2-BMDMs polarization, and delineated new insights into the immune interplay underlying inflammatory bowel disease." (PMID 27094081, 2016). "Octanoic acid‐rich enteral nutrition could regulate the M1/M2 polarization of intestinal macrophages and simultaneously repair the intestinal mucosal barrier by activating the PPARγ/STAT‐1/STAT‐6 pathway, thereby significantly alleviating inflammatory bowel disease‐induced intestinal injury." (PMID 41256230, 2025). "This study aimed to investigate whether activation of PPARγ regulates M1/M2 macrophage polarization to attenuate dextran sulfate sodium salt (DSS)‐induced inflammatory bowel disease (IBD) via the STAT‐1/STAT‐6 pathway in vivo and in vitro." (PMID 39737788, 2025).